SPHK1 (sphingosine kinase 1)
Diseases named in the same sentence as SPHK1 in open-access papers (continued):
Sharing a sentence is not in itself a finding about the gene and the disease.
breast carcinoma (continued). "We validated the higher expression of SPHK1 mRNA levels in triple-negative human breast tumors compared to receptor-positive tumors, which correlate with poor overall and progression-free survival in breast cancer patients." (PMID 25153718, 2014). "A combination of SPHK1 inhibitors with chemotherapeutic agents may be effective against this aggressive subtype of breast cancer." (PMID 25153718, 2014). "In addition, the effects of SPHK1 inhibition by SKI-5C on the proliferation of breast cancer cells were examined by BrdU assay." (PMID 25153718, 2014). "On the other hand, EGF can stimulate the activity of SphK1 in breast cancer cells." (PMID 24970174, 2013). "Moreover, our group recently reported that SphK1-produced S1P promotes angiogenesis and lymphangiogenesis and facilitates breast cancer progression." (PMID 24286034, 2013). "Furthermore, epimesatines P, R, and S were found to significantly inhibit the expression of Sphk1 in MCF-7 cells, suggesting that Sphk1 may serve as a target for breast cancer treatment." (PMID 39407639, 2024). "Moreover, SphK1 increased radiochemotherapy drug resistance in breast cancer." (PMID 36909198, 2023). "Consistent with clinical findings, studies have demonstrated that targeting SPHK1 using RNAi-mediated approaches or pharmacological SPHK1 inhibitors can reduce cell proliferation, induce apoptosis, synergize chemo- and endocrine sensitivity, impede invasion, and decrease metastasis in breast cancer." (PMID 34820423, 2021). "SPHK1 overexpression, for instance, has been described in different cancer subtypes both in in vivo and in vitro studies, and its role in tumor initiation, progression (e.g., angiogenesis) and metastasis has been shown, e.g., in lung cancer, breast cancer, pancreatic cancer and colorectal cancer." (PMID 33660008, 2021). "However, in breast cancer cells, studies have shown an upregulation of SphK1/SphK2." (PMID 33758708, 2021). "Hence, it is required to identify more influential inhibitors that selectively inhibit SphK1 and lead to apoptosis and growth arrest in breast cancer cells without causing cytotoxic impact in healthy cells." (PMID 31752564, 2020). "Similarly, the presence of S1P induces Notch signaling and augments mammosphere-forming capacity in breast CSCs, and S1P3 is highly expressed in ALDH-positive cells derived from breast cancer patients, suggesting that the SPHK1/S1P/S1P3 axis is important for the maintenance of stem-like features." (PMID 32260399, 2020). "Moreover, our preclinical findings suggest that co-targeting IGF1R and SphK1 may have benefit in some women with breast cancer and requires further investigation." (PMID 29207959, 2017). "Furthermore, our microarray analysis revealed significantly elevated levels of SPHK1 in poor responders to Doxorubicin/Doxetaxel-based chemotherapy, showing that SPHK1 may play a critical role in breast cancer resistance to chemotherapy." (PMID 25153718, 2014). "Moreover, SPHK1 has been shown to have a prognostic significance in breast cancer." (PMID 23981902, 2013). "Subsequently, we further narrowed down the eight candidate genes (TRIM47, SPHK1, RGMA, ROPN1B, LARP6, ROPN1, NPM2 and LPL) that are shared in TNBC compared to ER+ and HER2+ breast cancer subtypes in cancer cells." (PMID 40635123, 2025). "Another study found that in breast cancer MCF-7 cells, SPHK1 induces autophagy by increasing the formation of LC3-positive autophagosomes, thereby protecting them during nutrient deprivation." (PMID 37190124, 2023). "Sphingosine kinase 1 (SPHK1) inhibits RANKL-induced p38 activation, thereby hindering osteoclast maturation and breast cancer bone metastasis." (PMID 37860014, 2023). "Our reanalysis of a published microarray dataset showed that compared to other subtypes of breast cancer, TNBC patient samples exhibited elevated mRNA expression levels of SPHK1 yet the decreased expression of SPHK2." (PMID 37048053, 2023).
breast carcinoma (continued). "S1P/SPHK1 interacts with constituents in TME and modulate the progression and metastasis of breast cancer." (PMID 34283088, 2021). "The aim of the current study was to characterize and compare the effects of specific SphK1-activating agents on the intracellular localization of SphK1 and S1P3 in ER-positive MCF-7 breast cancer cells and MCF-7-derived, BCSC-enriched mammospheres." (PMID 33919234, 2021). "SphK1 also leads to the enhanced growth factor receptor (EGFR) transactivation, via estrogen (E2) induction in human breast cancer cells." (PMID 35201458, 2021). "Sphingolipids were identified in breast cancer patients, and genes related to metabolism, such as CERK, SPHK1, and SGMS1, were verified by a TCGA cohort." (PMID 34549263, 2021). "In this review, we first explore the oncogenic functions of sphingosine kinase 1 in human cancers and summarize current research findings of SPHK1 signaling with a focus on breast cancer." (PMID 34820423, 2021). "have reported SphK1 and S1P3 nuclear translocation due to the action of S1P and estrogen results in the cell proliferation in MCF-breast cancer cell lines and vice versa on inhibition." (PMID 35201458, 2021). "Many have also attempted to investigate the involvement of S1PRs in the signaling cascades of SPHK1/S1P axis in human cancers, whereby substantial evidence has highlighted the interactions between SPHK1/S1P axis with S1PR1, S1PR3, and S1PR4 in breast cancer." (PMID 34820423, 2021). "In summary, the signaling network modulated by SPHK1/S1P axis is interwoven with various S1PR-dependent and S1PR-independent signaling pathways in breast cancer cells." (PMID 34820423, 2021). "ISO-mediated downregulation of SPHK1/2 and increased tubulin destabilization can be the major targets involved in the strong anti-cancer effect of ISO against breast cancers." (PMID 31817453, 2019). "The detected clinical data suggest pathway interactions, potentially of a mutually-exclusive capacity among ERs, SphK1, and HER2-signaling in breast cancer cells." (PMID 29385066, 2018). "Ohotski et al36 also indicated that nuclear localization of sphingosine kinase 1 and S1PR2 played an important role in breast cancer prognosis." (PMID 29923327, 2018). "Several proteins that interact with SPHK1 in MCF-7, a breast cancer cell line, were identified demonstrating their involvement with cell migration, adhesion and cytoskeletal remodeling." (PMID 29186783, 2017). "The prognostic (overall survival, OS) and therapeutic (anti-endocrine therapy) co-contribution of IGF1R and SphK1 were investigated using breast cancer patient samples (n = 236) for immunohistochemistry to measure total and phosphorylated IGF1R and SphK1." (PMID 29207959, 2017). "This study has identified novel relationships between breast cancer patient survival outcome and ER, PR and HER2 status and anti-estrogen therapy, based on IGF1R and SphK1 protein expression." (PMID 29207959, 2017). "Correlation analysis was used to identify the relationship between the SPHK1 expression and cytokines levels, and results indicated a positive correlation between SPHK1 and TNF-α in breast cancer, r = 0.5287, p = 0.0352." (PMID 29186783, 2017). "At the molecular level, IGFBP3 activated SphK1 and led to S1P-dependent transactivation of EGFR in normal mammary epithelial and breast cancer cells." (PMID 29108245, 2017). "Since expression of SphK1 in the triple negative (TN) cancer cell line, MDA-MB-231 was upregulated in stiff substrate in our results, we anticipated that breast cancer cells would increase SphK1 levels in stiff substrates." (PMID 26877098, 2016). "In particular, the interaction between SPHK1 and S1PR1 has been shown to be altered during ovarian and breast cancer development in a variety of ways and therefore may be an attractive therapeutic target." (PMID 39767749, 2024).
breast carcinoma (continued). "Furthermore, breast cancer cell-derived CST6 enters osteoclasts through endocytosis and upregulates the hydrolysis substrate of CTSB, SPHK1, by inhibiting CTSB." (PMID 37860014, 2023). "Similarly, the expression of SphK1 is positively correlated with poor OS and progression‐free survival (PFS) of breast cancer." (PMID 35184376, 2022). "When we subdivided the breast tissue samples into ER positive and ER negative status, ER positive breast cancers were more likely to express both SphK1 isoforms." (PMID 36532885, 2022). "Moreover, studies have indicated that SPHK1/S1P/S1PR3 signaling axis promotes tumorigenicity and metastasis of breast cancer by activating p38 mitogen-activated protein kinase (MAPK)/Notch signaling." (PMID 34820423, 2021). "Taken together, it is believed that SPHK1/S1P/S1PR1 axis by interacting with inflammatory cytokine amplification loops, could have prominent roles in the progression of inflammation-driven breast cancers." (PMID 34820423, 2021). "The effect of TNFα on the enzymatic activity of SphK1/2 in MCF-7 breast cancer cells was never tested comprehensively." (PMID 33919234, 2021). "Furthermore, studies have suggested that SPHK1/S1P/S1PR1 signaling pathway also aids to mediate treatment-induced inflammation and resistance to doxorubicin and tamoxifen in breast cancer, which is also accompanying with upregulation of NF-κB/IL-6/STAT3." (PMID 34820423, 2021). "Alshaker and colleagues demonstrated that leptin as an adipokine was able to induce upregulation of SPHK1 and in turn SPHK1 could contribute to leptin-induced STAT3 activity in breast cancer via transactivation of IL-6/gp130." (PMID 34820423, 2021). "While SPHK1 signaling axis has been extensively studied in non-stem breast cancer cells, recent evidence has emerged to suggest a role of SPHK1 in regulating cancer stem cells (CSCs)." (PMID 34820423, 2021). "Our study revealed the clinically meaningful difference of the circulating S1P levels in breast cancer patients by measuring S1P directly, rather than measuring expression levels of SphK1, an S1P-producing enzyme." (PMID 34948163, 2021). "A remarkable finding is that SPHK1 and SPHK2 expression among the different breast cancer subtypes is highly variable, making it difficult to generalize about the implication of these enzymes in breast cancer." (PMID 35004331, 2021). "Overall, our results implicate SPHK1 as a potential target for the treatment of refractory breast cancers by targeting both breast CSCs and non-CSCs." (PMID 32260399, 2020). "Collectively our findings suggested a novel role for SPHK1 in attenuating STAT1-mediated IFN signaling, and therapies targeting this signaling axis may be beneficial to breast cancer patients." (PMID 32260399, 2020). "To investigate whether the SPHK-S1P axis is altered in breast CSCs, we evaluated the basal expression levels of SPHK1, phosphorylated SPHK1, and SPHK2 in a panel of breast CSCs derived from MCF-7, SKBR3, MDA-MB-468, and HCC38 breast cancer cells." (PMID 32260399, 2020). "Moreover, inhibition of SPHK1/2 and induction of tubulin destabilization by ISO greatly influenced breast cancer cell death and growth." (PMID 31817453, 2019). "Accordingly, it was suggested that SphK1 can regulate cell responsiveness to S1P by increasing S1PR3 expression levels, thus producing a positive amplification loop of S1PR3-mediated invasive signaling in breast cancer cells." (PMID 29385066, 2018). "Notably, both SphK isoenzymes were equally responsible for insulin-induced cell cycle progression and the proliferation of MCF-7 breast cancer cells, although SphK1 and SphK2 had different roles in mediating insulin-induced ERK1/2 and Akt activation." (PMID 29385066, 2018). "In ERα-negative breast cancer cell lines MDA-MB-231 and BT-549 Src, family kinases were linked to leptin-induced SphK1 effects." (PMID 29385066, 2018).
breast carcinoma (continued). "The level of SPHK1 and its product S1P is elevated in multiple cancers, including breast cancer, especially in ER and PR negative tumors." (PMID 29531546, 2017). "The current study data suggested a significant difference between SPHK1 expression level in negative receptor of estrogen and progesterone, compared with the positive receptors of breast cancer (P-value=0.0177)." (PMID 29531546, 2017). "We conclude that high IGF1R and SphK1 co-expression act together as prognostic indicators and are potentially, dual therapeutic targets for the development of a more effective IGF1R-directed combination breast cancer therapy." (PMID 29207959, 2017). "However, several breast cancer cell lines including TN breast cancer cell lines such as Hs578T and BT20 decreased the SphK1 expression in stiff substrate." (PMID 26877098, 2016). "Interestingly, normal breast epithelial cell lines, MCF10A, and primary breast cancer cell lines, Hs578T and BT20, showed the expression of SphK1 expression in stiff substrates was decreased by 15%, 16%, and 23% compared with soft substrates, respectively." (PMID 26877098, 2016). "Sphingosine kinase 1 (SK1) is an oncogenic lipid kinase that is overexpressed in breast tumours and linked with poor prognosis, however, its role in obesity-driven breast cancer was never elucidated." (PMID 25482303, 2014). "In our studies, up-regulation of SPHK1 in TNBC was identified by several lines of evidence, including comparative determination of SPHK1 expression in breast cancer tissues and cell lines, as well as microarray data of human breast cancers from Affymetrix U133A and U133Plus2 platforms." (PMID 25153718, 2014). "Since both HER2 and SphK1 are strong activators of survival signaling pathways, such as the MAPK pathway, and the HER2 signaling is highly autonomous, it is possible that negative feedback from HER2 signaling suppresses SphK1 activation in HER2-positive breast cancer." (PMID 38542328, 2024). "The expression of SPHK1 was observed to have no impact on OS among various breast cancer subgroups." (PMID 36309544, 2022). "However, SphK1 signaling was suppressed in HER2 positive breast cancer, likely by a negative feedback mechanism that favors only one survival and proliferation enhancing pathway." (PMID 29385066, 2018). "Furthermore, since IGF1R is an established oncogenic factor in breast cancer and has been the focus of numerous clinical trials, it is potentially of therapeutic importance that we have shown that co-targeting both IGF1R and SphK1 in vitro has a synergistic benefit." (PMID 29207959, 2017). "Similarly, miR-98 expression downregulates activin receptor-like kinase-4 (ALK4) and metalloproteinase-11 (MMP11) expression, and miR-506 downregulates Sphingosine kinase 1 (SPHK1), thereby inhibiting cell growth and angiogenesis in breast cancer and hepatoma cell models, respectively." (PMID 27231010, 2016). "Interestingly, in breast cancer MCF-7 cells, SphK2, but not SphK1, was associated with histone H3 and on stimulation with phorbol ester produced S1P." (PMID 23028939, 2012). "Similarly, SPHK1 was also not found to correlate with the OS of breast cancer patients." (PMID 36309544, 2022). "Considering that both HER2 and SphK1 are strong activators of survival signaling pathways such as MAPK, and HER2 signal is a strong autonomous signal, it is tempting to speculate that negative feedback suppresses activation of SphK1 in HER2-positive breast cancer." (PMID 28912626, 2017). "The current study aimed at investigating whether SPHK1 is expressed highly in ER and PR negative compared to ER and PR positive breast cancers and their normal tissue, and also the relationship of this expression with BMI in patients with breast cancer." (PMID 29531546, 2017).
breast carcinoma (continued). "While our studies support extrinsic signal-regulated translocation of SphK1 to the nucleus in MCF-7 cells, differential mechanisms controlling this process in non-stem breast cancer cells and BCSCs require further investigation." (PMID 33919234, 2021). "On the other hand, knockdown of SphK2, but not SphK1, in U1242 and U87 MG glioblastoma cells attenuated cell proliferation and doxorubicin-induced apoptosis in MCF7 breast cancer cells." (PMID 23028939, 2012). "PF-543, a selective, potent inhibitor of SphK1, attenuated epidermal growth factor-mediated cell growth and survival signaling through inhibition of AKT, ERK, and p38 MAP kinase pathways in LM2-4 cells, but not in the parental MDA-MB-231 human breast cancer cells." (PMID 28912626, 2017).